LRRC4C (leucine rich repeat containing 4C)
Description:
May promote neurite outgrowth of developing thalamic neurons.
Synonyms: NGL-1; KIAA1580; NGL1
Tractability: Small molecule: it belongs to a druggable protein family. Antibody: UniProt places it where antibodies can reach, with high confidence; UniProt predicts a signal peptide or a membrane-spanning region; its Gene Ontology location is reachable by antibodies, with medium confidence. PROTAC: its protein half-life has been measured.
Gene: Protein-coding gene on chromosome 11 (40,113,474 to 41,459,773, reverse strand). Ensembl gene ENSG00000148948.
Subcellular location: Postsynaptic cell membrane
Subcellular location (Human Protein Atlas): Cytosol
Gene Ontology:
Molecular function: cell adhesion molecule binding; cell-cell adhesion mediator activity; protein binding
Biological process: regulation of axonogenesis; synaptic membrane adhesion; modulation of chemical synaptic transmission
Cellular component: extracellular region; membrane; glutamatergic synapse; plasma membrane; postsynaptic density membrane; postsynaptic membrane; Schaffer collateral - CA1 synapse
Genetic constraint (gnomAD): Loss-of-function variants: 5 observed, 35.42 expected, observed/expected ratio (o/e) 0.14, 90% interval 0.073 to 0.3. The upper end of that interval is the gene's LOEUF score, 0.3, which puts it in group 1 of 6, group 1 being the genes least tolerant of losing a copy. Missense variants: 560 observed, 838.74 expected, observed/expected ratio (o/e) 0.67, 90% interval 0.62 to 0.72. Synonymous variants: 329 observed, 319.17 expected, observed/expected ratio (o/e) 1.03, 90% interval 0.94 to 1.13.
Homologues: Orthologues: chimpanzee LRRC4C (100% identical), macaque LRRC4C (100% identical), rabbit LRRC4C (99% identical), guinea pig LRRC4C (99% identical), mouse Lrrc4c (99% identical), pig LRRC4C (99% identical), rat Lrrc4c (99% identical), tropical clawed frog lrrc4c (88% identical), zebrafish lrrc4ca (80% identical), zebrafish lrrc4cb (72% identical). Paralogues in human: LRRC4B (64% identical), LRRC4 (55% identical), FLRT1 (21% identical), FLRT2 (21% identical), FLRT3 (20% identical), LRRTM4 (18% identical), LRRTM3 (17% identical), LRRC15 (17% identical), RTN4R (17% identical), LRRC66 (15% identical), RTN4RL1 (15% identical), PODN (15% identical), and 10 more.
Diseases named in the same sentence as LRRC4C in open-access papers:
LRRC4C is named in the same sentence as 28 diseases in open-access papers, as found by Europe PMC text mining. Sharing a sentence is not in itself a finding about the gene and the disease. The quoted sentences say what the papers report.
autism (4 papers, 2020 to 2022). Persistent deficits in social interaction and communication and interaction as well as a markedly restricted repertoire of activity and interest as well as repetitive patterns of behavior. "An individual who had a sensory processing disorder, apraxia, and autism, and was from a family with a variable psychiatric disorder, had mutation and disruptions in both DPP6 and LRRC4C genes, even though the variant by itself was not cause the autism." (PMID 36012450, 2022).
Anxiety (2 papers, 2019 to 2022). Intense feelings of nervousness, tension, or panic often arise in response to interpersonal stresses. "Lrrc4c knockout mice display hyperactivity and anxiety-like behaviors." (PMID 36395078, 2022).
bipolar disorder (2 papers, 2019 to 2023). A disorder of the brain that causes unusual shifts in mood, energy, activity levels and the ability to carry out day-to-day tasks. "Netrin-G ligand-1 (NGL-1), encoded by Lrrc4c, is a post-synaptic adhesion molecule implicated in various brain disorders, including bipolar disorder, autism spectrum disorder, and developmental delay." (PMID 31680855, 2019). "Specifically, it has been shown that LRRC4C (encoding NGL-1) is weakly associated with three types of temperaments—hyperthymic, dysthymic and cyclothymic—that enhance the risk of bipolar disorder." (PMID 31680855, 2019). "This is particularly important because NGL-1/LRRC4C has been implicated in various brain disorders, including bipolar disorder, ASD, and developmental delay." (PMID 31680855, 2019).
epilepsy (2 papers, 2019 to 2022). A brain disorder characterized by episodes of abnormally increased neuronal discharge resulting in transient episodes of sensory or motor neurological dysfunction, or psychic dysfunction. "Many of these genes are associated with epilepsy and ictogenesis, including DPP10, DOCK8, IAH1, LRRC4C, and SLC6A5." (PMID 36506088, 2022).
myopia (2 papers, 2013 to 2022). "These vQTLs are strong candidates for having either GxE or GxG interaction effects and, indeed, genetic variants located near the GJD2, LAMA2, RBFOX1, KCNQ5 and LRRC4C genes were associated with a progressively increasing risk of myopia as the number of years of schooling rose." (PMID 36395078, 2022).
schizophrenia (2 papers, 2019 to 2023). A major psychotic disorder characterized by abnormalities in the perception or expression of reality. "It is further interesting that at least three of these genes (ADAMTS1, LRRC4C, and LRRC7) have already been associated with schizophrenia." (PMID 37244930, 2023). "At least seven genes putatively mapped by our significant non-reference TEs have been already associated with schizophrenia: LRRC4C, LRRC7, ST8SIA4, MGAM, ADAMTS1, MIR548AJ2 and SCN5A, which is also linked to the Brugada syndrome." (PMID 37244930, 2023).
colon cancer (1 paper, 2021). "Combined with our results, we have more reason to believe that LRRC4C is involved in the tumour progression of colon cancer and gastric cancer in a similar way to LRRC4." (PMID 33867855, 2021).
gastric cancer (1 paper, 2021). A primary or metastatic malignant neoplasm involving the stomach. "Single-gene survival analysis using Gene Expression Profiling Interactive Analysis 2.0 and Kaplan-Meier plotter revealed an association between high levels of LRRC4C expression and poor prognosis in patients with colon and gastric cancers." (PMID 33867855, 2021). "We demonstrated that LRRC4C is a prognostic marker of colon and gastric cancer and is involved in immune-related activities." (PMID 33867855, 2021). "More importantly, LRRC4C may participate along with monocytes, M2 macrophages, and resting mast cells in the construction of the TME in patients with colon and gastric cancers." (PMID 33867855, 2021).
glioma (1 paper, 2021). A benign or malignant brain and spinal cord tumor that arises from glial cells (astrocytes, oligodendrocytes, ependymal cells). "Leucine-rich repeat-containing protein 4C (LRRC4C) is involved in the inhibition of glioma, induction of the antitumor immune response, and activation of natural killer cells in the destruction of tumor cells." (PMID 33732214, 2021).
mucinous adenocarcinoma (1 paper, 2021). An invasive adenocarcinoma composed of malignant glandular cells which contain intracytoplasmic mucin. "Similarly, increased LRRC4C expression was observed in colon mucinous adenocarcinoma samples compared with adenocarcinoma samples (p = 0.0008; Student's t-test)." (PMID 33867855, 2021).
myocarditis (1 paper, 2024). Myocarditis is a condition that is characterized by inflammation of the heart muscle (myocardium). "These regions localized to Bone Morphogenetic Protein 3 (BMP3) and Leucine-Rich Repeat Containing 4 C (LRRC4C), suggesting a potential connection between these genomic regions and vaccine-related myocarditis." (PMID 38844841, 2024).
tumor (7 papers, 2020 to 2023). "To explore the relationship between LRRC4C and different types of tumours, we examined LRRC4C expression in various human cancers using RNA-seq data from the TIMER2.0 database." (PMID 33867855, 2021). "Difference and correlation analyses of the relationship between LRRC4C expression and tumour-infiltrating immune cells, determined using CIBERSORT algorithms, revealed that monocytes, resting mast cells, and M2 macrophages were positively correlated with LRRC4C expression." (PMID 33867855, 2021).
neurodevelopmental disorder (3 papers, 2018 to 2022). A behavioral and cognitive disorder with onset during the developmental period that involves impaired or aberrant development of intellectual, motor, or social functions. "The gene LRRC4C has been reported to be involved in the regulation of axon development and synaptic development, and its deficit can cause neurodevelopmental disorders." (PMID 33304381, 2020). "The netrin family gene LRRC4C, which was decreased in MUTex8 and MUTex12 by RNAseq (but did not meet threshold for whole-transcriptome significance) and in MUTex12 by qRT-PCR, has been associated with neurodevelopmental disorders in genetic studies." (PMID 30410030, 2018).
brain disorder (2 papers, 2019). A disease affecting the brain or part of the brain. "Some of the synaptic phenotypes that are associated with Lrrc4c deletion identified in the present study might underlie these NGL-1-related brain disorders." (PMID 31156385, 2019).
cancer (2 papers, 2021). A tumor composed of atypical neoplastic, often pleomorphic cells that invade other tissues. "The relationship between LRRC4C expression and survival in 33 cancer types was analysed." (PMID 33867855, 2021).
LRRC4C also shares sentences with these, for which no sentence is quoted: glioblastoma (2 papers); pancreatic cancer (2); Rett syndrome (2); adenocarcinoma (1); Anorexia (1); autism spectrum disorder (1); breast carcinoma (1); Brugada syndrome (1); colon (1); COVID-19 (1); depression (1); developmental delay (1); Intellectual disability (1).